INS (insulin)
Diseases named in the same sentence as INS in open-access papers (continued):
Sharing a sentence is not in itself a finding about the gene and the disease.
type 2 diabetes (continued). "The treatment with IG-1 for 7 or 28 days reduces daily food intakes, body weights, and fasting plasma concentrations of glucose, insulin, triglyceride and free fatty acids, and hepatic triglyceride contents in mice models of type 2 diabetes, obesity and metabolic syndrome." (PMID 24971987, 2014). "Then we investigated whether exposure to LDR could attenuate dyslipidemia, inflammation and oxidative stress and enhanced insulin sensitivity in type 2 diabetes." (PMID 24651118, 2014). "In this cross-sectional study, we investigated the association between sUA and β-cell function as well as insulin sensitivity in patients with type 2 diabetes, and we further elucidate the time-dependent changes of insulin secretion ability in different gender and uric acid level groups." (PMID 24971368, 2014). "However, some type 2 diabetes insulin users are also in need of a similar self-management intensity." (PMID 25499872, 2014). "The fourth study was a randomized, two-period crossover, open-label, active-controlled study with two treatment periods of 3 months each and involved patients with type 2 diabetes who had been receiving human insulin for at least 2 months prior to enrolling in this study." (PMID 23959960, 2014). "This hypothesis is in line with recent studies showing that the use of hypoxia during exercise training additively improves insulin sensitivity in sedentary individuals and glycemic control in individuals with type 2 diabetes." (PMID 24887106, 2014). "Previous controlled trials comparing the combination therapy with oral hypoglycemic agents (SU plus Metformin) and insulin therapy in patients with poorly controlled type 2 diabetes are sparse, and among these studies, reports about a peakless, long-acting insulin analog are executive." (PMID 24614911, 2014). "In type 1 diabetes, the body fails to produce insulin, while type 2 diabetes is caused by insulin resistance." (PMID 25019556, 2014). "Other than insulin, it will require further investigation to identify novel therapeutic approaches, including strategies to inhibit adipogenesis in the fracture callus, to address impaired fracture repair in type 2 diabetes." (PMID 24911161, 2014). "The degree of self-management may be less in people with type 2 diabetes compared with those with type 1 diabetes because of the intensity of treatment and need for self-measuring of blood glucose levels by those who are insulin dependent." (PMID 25499872, 2014). "PANDER has been hypothesized to regulate fasting and fed glucose homeostasis, hepatic lipogenesis and insulin signaling, and to serve a potential role in the onset or progression of type 2 diabetes (T2D)." (PMID 25217499, 2014). "The results are consistent with the findings obtained from animal and clinical trials, which revealed that the consumption of whole grains may protect against type 2 diabetes by improving glucose control and insulin sensitivity." (PMID 24763110, 2014). "The reason why patients with type 2 diabetes of HUA group can secrete more insulin at the early stage was temporarily unknown." (PMID 24971368, 2014). "Moreover, in patients with type 2 diabetes, insulin infusion reduced the levels of eotaxin and MCP-1, and the eosinophil count is also related to albumin excretion in males." (PMID 24423092, 2014). "Accumulation of lipids within the liver may lead to reduced insulin signalling, impaired GLUT translocation and inflammation and is independently linked to type II diabetes." (PMID 24520329, 2014). "Insulin secretion and action are assessed using frequently sampled OGTTs in non-diabetic participants, and frequently sampled mixed-meal tolerance tests in patients with type 2 diabetes." (PMID 24695864, 2014).
type 2 diabetes (continued). "Current treatment options for type 2 diabetes can be categorized into three main classes: biguanides, which mainly inhibit gluconeogenesis; insulin sensitizers, which promote insulin action; and insulin secretagogues or insulin itself, which raise insulin levels." (PMID 24533087, 2014). "In addition, infusion of HDL in patients with type 2 diabetes increased both insulin secretion and glucose clearance." (PMID 24442447, 2014). "Intensive treatment of type 2 diabetes, usually based on insulin, has not so far demonstrated a positive risk-benefit ratio." (PMID 24752580, 2014). "Glucose transport is the rate-limiting step for glucose metabolism in healthy and diabetic individuals, with decreased insulin-stimulated glucose uptake into skeletal muscle being a major contributory factor to insulin resistance in patients with type 2 diabetes." (PMID 24849570, 2014). "Serum NEFA concentration is a risk factor for type 2 diabetes because the combination of excessive levels of non-esterified fatty acids and glucose leads to decreased insulin secretion, impairments in insulin gene expression and beta-cell death by apoptosis." (PMID 25534067, 2014). "Resistant starch (RS) has been shown to beneficially affect insulin sensitivity in healthy individuals and those with metabolic syndrome, but its effects on human type 2 diabetes (T2DM) are unknown." (PMID 24671124, 2014). "Exercise has also been shown to increase insulin sensitivity in patients with type 2 diabetes." (PMID 24775272, 2014). "For those having longer type 2 diabetes duration and being diagnosed the failure of insulin secretion, the clinicians may recommend the insulin injections alone." (PMID 25202328, 2014). "According to our results, ruscogenin could positively influence fatty liver changes in type 2 diabetes and in insulin resistant state." (PMID 25136608, 2014). "Type 2 diabetes is characterized by both decreased insulin secretion and sensitivity." (PMID 24684803, 2014). "Indeed, roughly 25% of patients with type 2 diabetes require exogenous insulin within 6 years of diagnosis, and 42% within 10 years." (PMID 24695864, 2014). "In type 2 diabetes (T2D), the most prevalent form of the disease, the defect in glucose metabolism is the result of decreased sensitivity of peripheral tissues to insulin action, accompanied by failure of β-cells to compensate for the increased metabolic demand." (PMID 25071830, 2014). "Vaspin was identified as an adipokine with insulin-sensitizing effects, which is predominantly secreted from visceral adipose tissue in a rat model of type 2 diabetes and has been shown to significantly reduce blood glucose concentrations in various mouse models." (PMID 23370777, 2013). "People with type 2 diabetes receiving sulphonylureas have reported hypoglycaemia in comparable proportions to those receiving insulin for less than 2 years, with 7% in both groups reporting severe hypoglycaemia and 39 and 51%, respectively, reporting mild hypoglycaemia." (PMID 23121373, 2013). "Insulin replacement therapy with type 2 diabetes may be required for most patients during the duration of their disease." (PMID 23433347, 2013). "Over time, these disturbances could alter the oxidant tone and create a cellular environment incapable of effective insulin signaling and glucose uptake, ultimately manifesting in type 2 diabetes." (PMID 23603996, 2013). "Furthermore, PED/PEA-15 protein levels negatively correlate to insulin sensitivity in offsprings of Type 2 diabetics." (PMID 23585839, 2013). "The relentless, progressive nature of Type 2 diabetes results in an almost inevitable need for insulin supplementation and its intensification in an attempt to combat a worsening glycaemic profile 1,2, including glycaemic variability 3 and the associated increased risk of vascular complications 4–7." (PMID 22998363, 2013).
type 2 diabetes (continued). "A recent observational study was performed on 122 persons with type 2 diabetes, 61 were treated with oral hypoglycaemic agents alone, and 61 were treated with a combination of oral hypoglycaemic agents and insulin at either a low dose (<0.40 unit/kg/day) or high dose (≥0.40 unit/kg/day)." (PMID 23577222, 2013). "Further study is needed to determine if lower insulin sensitivity in AA women is associated with greater risk for type 2 diabetes, even in the absence of obesity." (PMID 23298367, 2013). "Expression of Ppargc1a is reduced in insulin resistant tissues, during obesity and in type 2 diabetes; and Ppargc1a knock-out mice exhibit hepatic steatosis due to a reduction in mitochondrial oxidative capacity and mtDNA content, together with an upregulation of lipogenic gene expression." (PMID 23783067, 2013). "This dose was markedly lower than that of other regimens, including short-term CSII therapy, indicating that insulinization may not only control blood glucose rapidly, but also reduce the total dosage of insulin during the treatment of type 2 diabetes." (PMID 24223662, 2013). "Thus, this study was designed to evaluate the effect of insulin analog initiation therapy on n6 and n3 PUFAs in type 2 diabetic patients during early phase." (PMID 24195588, 2013). "Overall, 140 patients with type 2 diabetes on insulin therapy were included in our study." (PMID 23383010, 2013). "Insulin therapy has been integrated into the treatment of type 2 diabetes." (PMID 24223662, 2013). "Insulin is widely used to treat type 2 diabetes because numerous studies indicate that it works." (PMID 23841986, 2013). "Their management always involves insulin administration, whereas type 2 diabetes patients may be managed using lifestyle changes and oral hypoglycemic agents." (PMID 24250826, 2013). "Type 2 diabetes mellitus is characterized by resistance to insulin." (PMID 23601582, 2013). "Importantly, α-lipoic acid is known to activate AMPK and has been effectively used to increase insulin sensitivity in type 2 diabetic patients." (PMID 23565271, 2013). "The main purpose of this pilot study was to evaluate a combination of EA and drug therapy, namely, treatment with the insulin sensitizer, rosiglitazone, and to explore whether this improves insulin activity among type 2 diabetic patients." (PMID 23983807, 2013). "Overall, results from the OPAL study demonstrated that the introduction of a single bolus dose of prandial insulin, added to basal insulin and oral anti-diabetic drugs, had the potential to offer a simple and effective means of intensifying insulin therapy in people with Type 2 diabetes." (PMID 22998363, 2013). "The characteristics of AT1R inhibitors in both insulin and glucagon secretion could make it a potential novel therapeutics for the prevention and treatment of type 2 diabetes." (PMID 24371439, 2013). "Clinical trials have been shown that LA improved glucose metabolism in diabetic patients and LA treatment also increased insulin sensitivity in type-2 diabetic patients and enhanced glucose transport into skeletal muscle isolated from both obese and lean Zucker rats." (PMID 24298385, 2013). "This could be of clinic interest, since a typical feature of type 2 diabetes is a reduced ability to secrete insulin in response to a meal." (PMID 24312178, 2013). "Therefore the present study sought to assess the role of insulin in L-arginine transport and endothelial function under normal conditions and in type 2 diabetes." (PMID 23658699, 2013). "Exercise improved insulin sensitivity in the lean, obese, and type 2 diabetes groups." (PMID 23671849, 2013). "Among people with type 2 diabetes receiving oral antidiabetes drugs under employer-sponsored Medicare supplemental plans, not excluding those using insulin, hypoglycaemia has been associated with increased risk of fall-related fractures." (PMID 23121373, 2013).
type 2 diabetes (continued). "Type 2 diabetes (T2D) originate from abnormalities in both glucose and lipid metabolism leading to β-cell failure to compensate insulino-resistance and adequately secrete the insulin necessary to maintain glucose and lipid homeostasis." (PMID 23383107, 2013). "Our results suggested that administration of Lr263 could prevent the development of type 2 diabetes by normalizing serum levels of glucose, insulin, C-peptide and leptin." (PMID 23590862, 2013). "Similarly, the pathophysiology of hepatocyte ballooning injury in Zucker diabetic fatty rats (ZDFs), a model characterized by obesity and type-2 diabetes, with aberrant hepatic response to insulin and impaired hepatic lipid metabolism remains largely unclear." (PMID 24260182, 2013). "During hyperglycaemia (i.e., type 2 diabetes and/or obesity) the eCB-system in pancreatic islets becomes dysregulated and may disrupt the regulatory loop between insulin and eCB." (PMID 23393605, 2013). "The results suggest that we found poor sleep quality in female Chinese type 2 diabetes patients with insulin treatment and these findings may contribute to sleep disorder control in female type 2 diabetes." (PMID 23383010, 2013). "GPR40 knockout mice could prevent HFD induced-hyperinsulinemia to keep a lower insulin level in the early stage of type 2 diabetes." (PMID 23776696, 2013). "Among the alkaloids, III demonstrated the most potent activity in PTP-1B inhibition, which supports further development of III as a novel PTP-1B inhibitor that may serve as “insulin sensitizer” in the management of type 2 diabetes." (PMID 23955322, 2013). "Furthermore, miR-29 was highly expressed in muscle, fat and liver of type 2 diabetes rats and overexpression of miR-29 attenuated insulin-induced Akt activation and glucose import." (PMID 24349318, 2013). "There was no excess risk of overall cancer in patients with type 2 diabetes who were treated with human insulin." (PMID 23308218, 2013). "Therefore, we conducted a cross-sectional study to determine the incidence of poor sleep quality in Chinese patients with type 2 diabetes using insulin therapy." (PMID 23383010, 2013). "In fact, chronic consumption of obesogenic diets induces a progressive deterioration in secretion of insulin by β-cells which may give way to type-2 diabetes during adulthood." (PMID 24205230, 2013). "Decreased insulin sensitivity in type 2 diabetes either by β-cells dysfunction or by obesity may affect the circulating lipids." (PMID 23690866, 2013). "While the incretin effect accounts for more than 50% of the meal-related insulin secretion in healthy individuals, its contribution to the overall insulin response after oral glucose ingestion may amount to <20% in patients with type 2 diabetes." (PMID 23717642, 2013). "Moreover, most studies concerning disturbances in insulin action with respect to physical activity and/or dietary habits concern middle-aged and/or older individuals with obesity and type 2 diabetes." (PMID 24348155, 2013). "Our findings were concordant with those studies that reported plasma glucose lowering activity of CAPA in STZ-induced type 1 diabetic mice and increased glucose transporter 4 protein expression along with insulin-induced glycogen synthesis in diet-induced type 2 diabetic mice." (PMID 23829275, 2013). "Thus, in addition to the documented analgesic effect of EA, we have shown in this study that there is a possible systemic effect of EA whereby there is modulation of FFA levels that can, in turn, influence insulin secretion in patients with type 2 diabetes." (PMID 23983807, 2013). "Therefore, this study was aimed to evaluate the effect of GP tea on insulin sensitivity by somatostatin-insulin-glucose infusion test (SIGIT) in drug-naïve type 2 diabetic patients." (PMID 23431428, 2013).
type 2 diabetes (continued). "In two randomized cross-over-designed trials, 18 insulin-treated type 2 diabetic patients with (Ejection Fraction (EF) 36±6%, n = 10) (trial 2) and without systolic heart failure (EF 60±3%, n = 8) (trial 1) were subjected to hyper- and normoglycemia for 9–12 hours on two different occasions." (PMID 23308171, 2013). "Previously, some but not all prospective studies showed an inverse association of risk of type 2 diabetes with intake of PUFA, and an intervention study also reported that a diet rich in LA improved insulin sensitivity compared with saturated fatty acid rich diet." (PMID 23741386, 2013). "Patients with type 2 diabetes may be trained as outpatients to use CSII and have indicated that they prefer CSII to injections, suggesting that pump therapy should be considered when initiating intensive insulin therapy for type 2 diabetes." (PMID 24223662, 2013). "TCF7L2 is involved in insulin secretion, and the TCF7L2 rs7903146 single nucleotide polymorphism (SNP) constitutes the best established risk allele in Caucasian populations conferring an overall relative risk for type 2 diabetes of 1.44." (PMID 24059590, 2013). "It is becoming increasingly evident that minor abnormalities occur in the insulin-resistant state that precedes the manifestation of overt type 2 diabetes, although IR patients were mostly investigated in the presence of co-morbidities and/or a long time after the initial diagnosis." (PMID 23590337, 2013). "This could represent improved hepatic insulin sensitivity or decreased pancreatic glucagon release with lowering of high endogenous fasting glucose production, as in type 2 diabetes." (PMID 23349861, 2013). "Similarly, Glargine has been shown to provide up to 24-hour glucose control than Neutral protamine Hagedorn (NPH) insulin in patients with type 2 diabetes." (PMID 23617853, 2013). "The weight-sparing property of insulin detemir is a phenomenon observed in several other studies in both Type 1 28 and Type 2 diabetes 33, but the reasons for this remain unclear." (PMID 23094597, 2013). "In many developed and developing countries, obesity has reached epidemic proportions, resulting in an increasing prevalence of type 2 diabetes characterized by insulin resistance of peripheral tissues such as liver, muscle, and fat which cannot be overcome by hypersecretion of pancreatic beta cells." (PMID 23762871, 2013). "Thus, the OSIRIS study confirmed that adding one injection of insulin glulisine to insulin glargine had similar efficacy and safety to a full basal–bolus regimen in Type 2 diabetes management." (PMID 22998363, 2013). "However, recent clinical and epidemiological studies demonstrate a role for some selenoproteins in exacerbating or promoting other disease states, specifically type 2 diabetes, although other data support a role of selenium in stimulating insulin sensitivity." (PMID 23603996, 2013). "The data presented here suggest that patients with type 2 diabetes undergoing hemodialysis and insulin therapy could be treated with incretin therapy in some cases." (PMID 23445717, 2013). "The basal-plus strategy is potentially suitable for a large number of individuals with Type 2 diabetes, and may delay their progression to a full insulin replacement regimen, especially when the initiation of insulin therapy is not delayed." (PMID 22998363, 2013). "The protective effects of physical activities include improved body composition, glucose tolerance, and insulin sensitivity, and this may have contributed to the decline in the incidence of type 2 diabetes since 2004, as determined in the present study." (PMID 23570503, 2013). "Metformin a biguanide enhances insulin sensitivity, found to be effective in impaired glucose tolerance, obese patients and patients with cardiovascular diseases and is used as first line of drug in treatment of Type II diabetes." (PMID 23351604, 2013).